IL10 (interleukin 10)
Diseases named in the same sentence as IL10 in open-access papers (continued):
Sharing a sentence is not in itself a finding about the gene and the disease.
COVID-19 (continued). "Our COVID-19 patients had significantly higher levels of IL-1β, IL-1Ra, IL-10, IFN-α2, IL-6, IL-18, and TNF-α than HC." (PMID 34367188, 2021). "An elevated level of CXCL-10/IL-10 in the patients of COVID-19 at Wuhan further evidenced the exacerbation of the innate immune response." (PMID 34305892, 2021). "Among these, IP-10, IL-10 and IL-6 have been proposed as a triad predictive of subsequent COVID-19 clinical progression." (PMID 34539631, 2021). "Patients with severe COVID-19 show increased levels of IL-6, IL-8, IL-10, IL-2R, and tumor necrosis factor (TNF)-α compared to those with mild to moderate disease." (PMID 34315546, 2021). "These included IL-33, IFN-α2, IFN-λ3, IFN-β and IFN-γ, which were decreased in the nasopharynx of patients with COVID-19, while IL-10 and CCL2 were increased, as compared to healthy controls." (PMID 34471264, 2021). "Monocyte rearrangement is likely to reflect the elevated IL-10 levels observed in COVID-19 patients." (PMID 34163490, 2021). "It was found that in mild COVID-19 patients, monocytes significantly increased IL-10 expression compared to healthy donors, and they were the dominant producers of IL-10." (PMID 33692788, 2021). "Concomitantly, the levels of cytokines such as IL-4, IL-6, and IL-10 are also increased in the sera of patients with COVID-19 compared with those of controls." (PMID 34360684, 2021). "Although IL-10 has anti-inflammatory properties, it cannot reverse the inflammatory storm induced by COVID-19." (PMID 33065551, 2020). "Results are explorative but indicate that DPSCs can down-regulate the production of cytokines by activated PBMCs, e.g., TNFα, IFNγ, IL-10, and IL-17A, which are up-regulated in COVID-19 patients." (PMID 33634100, 2020). "Those who proceeded to develop DHF had significantly higher IL-10 levels (p = 0.0003) compared to COVID-19 patients who developed severe illness." (PMID 33199778, 2020). "Both studies suggest that IL-6 and IL-10 are predictive factors of COVID-19 severity and progression." (PMID 33584667, 2020). "In particular, significantly higher levels of IL-6 and IL-10 have been identified in severe COVID-19 patients than in the milder forms, thus suggesting that these cytokines can be used to predict the transition from mild to severe infection." (PMID 32397174, 2020). "The levels of serum cytokines such as IL-6, IL-10, perforin, granulysin, sFas, and granzyme B in COVID-19 patients were significantly higher than those in healthy controls." (PMID 33154753, 2020). "Some of these studies focused on profiling cytokines in the peripheral blood of hospitalized patients with COVID-19, with one study reporting a significant increase in interleukin- (IL-) 6 and IL-10 in patients with severe cases of COVID-19." (PMID 33274223, 2020). "Nevertheless, contrasting to SARS cases, patients with COVID-19 also have elevated levels of Th2 cell-secreted cytokines (such as IL-4 and IL-10), which inhibit the inflammatory response." (PMID 33041985, 2020). "Hospitalized patients with severe COVID-19 show high levels of IL-2, IL-7, IL-10, G-CSF, TNF, CXCL10, MCP1, and MIP1α in serum, suggesting that severe COVID-19 is dictated as a cytokine release syndrome (CRS), which is a disorder induced by cytokine storms." (PMID 33014208, 2020). "For example, patients with severe COVID-19 had higher levels of IL-6, IL-2R, IL-10, and tumor necrosis factor alpha (TNF-α) than those with moderate disease, the former of which correlated with clinical severity and death." (PMID 33123165, 2020). "It was shown that those who developed severe COVID-19, were significantly more likely to have IL-10 levels of > 9.1 ng/L, which was seen in 35.8% of those with severe disease." (PMID 33199778, 2020). "In resting conditions, only IL-1β, IL-6, and IL-10 were detected in supernatants and showed similar levels between COVID-19 patients and healthy controls." (PMID 33634100, 2020).
COVID-19 (continued). "In patients with moderate COVID-19 the concentrations of IL-10, IL-6, and TNFα are within normal limits, and in the most severe patients they are very high." (PMID 32574327, 2020). "A prior study found that the number of T cells was drastically decreased, while the level of TNF, IL6, and IL10 were significantly increased in severe COVID-19 patients compared to healthy control." (PMID 33362771, 2020). "Although patients who developed severe pneumonia in COVID-19 had significantly higher levels of IL-10 than those with milder illness, patients who proceeded to develop DHF, had several fold higher levels during early illness." (PMID 33199778, 2020). "Our results showed significant increases in IL-6 and IL-10 in the peripheral blood of patients with severe cases of COVID-19 compared to the levels in patients with mild cases." (PMID 32669467, 2020). "Levels of fecal IL-8 were significantly elevated while levels of IL-10 were significantly lower in COVID-19 patients compared to uninfected controls, while the remaining tested cytokines were not significantly different." (PMID 32909002, 2020). "Elevated plasma concentration of inflammatory mediators was observed in patients with COVID-19, including IL-6, IL-10, TNF-α, and other inflammatory cytokines, as well as ferritin and C-reactive protein." (PMID 33552062, 2020). "Most patients with COVID-19 exhibit substantially elevated serum levels of pro-inflammatory cytokines, including IL-6, IL-2R, IL-8, IL-10 and TNFα, which is characterized as cytokine storms." (PMID 33365277, 2020). "Previously, small-scale studies have evaluated changes in IL-6 and CRP concentrations for COVID-19 patients, the correlation between IL-10 and CRP is still unclear." (PMID 32475230, 2020). "Compared to uninfected controls, COVID-19 patients had higher fecal levels of IL-8 and lower levels of fecal IL-10." (PMID 32909002, 2020). "Lymphopenia and the levels of IL-6, IL-10, and TNF-α were found to be negatively associated with COVID-19 patient survival." (PMID 32967229, 2020). "Despite the small number of such case during our study, it nevertheless highlights the importance of IL-6 and IL-10 as COVID-19 disease severity predictors." (PMID 32475230, 2020). "The higher fecal IL-8 and lower IL-10 concentration in COVID-19 patients compared to controls and the higher IL-23 in patients with severe disease point to some degree of immunological involvement of the GI tract in SARS-CoV-2 infection." (PMID 32909002, 2020). "Most importantly, COVID-19 induces a cytokine storm and lymphopenia, with elevation of cytokine levels such as the IL-2 receptor, IL-6, IL-8, IL-10 and necrosis factor tumor-alpha (TNF α), explaining SARS and multi-organ failure." (PMID 33327546, 2020). "We therefore examined the concentrations of serum cytokines, including TNF-α, IFN-γ, IL-2, IL-4, IL-6, and IL-10, from these COVID-19 patients to explore the influence of cytokine signaling." (PMID 32425950, 2020). "Analysis of COVID-19 patients revealed that IL-2, IL-6, IL-7, IL-10, granulocyte stimulating factor, interferon γ inducible protein 10, monocyte chemoattractant protein 1, macrophage inflammatory protein 1-α, and tumor necrosis factor α were increased." (PMID 32948238, 2020). "Higher plasma levels of cytokines, including interleukin (IL)-6, IL-2, IL-7, IL-10, and tumor necrosis factor-α, were found in patients with COVID-19, which implies the occurrence of a cytokine storm and its association with disease severity." (PMID 33335906, 2020). "Clinical studies have revealed that COVID-19 patients admitted to intensive care have increased expression of inflammatory cytokines (IL-6, IL-10, IL-2, and IFN-γ)." (PMID 33041797, 2020). "Low IFNγ response to the SARS-CoV2 and high levels of immunosuppressive IL-10 in both COVID-19 and dengue during early illness are indicators of an altered antiviral response potentially contributing to disease severity." (PMID 33199778, 2020).
COVID-19 (continued). "Another study including 21 COVID-19 cases reported that severe cases had increased IL-2R, IL-6, IL-10, and TNF-α when compared to moderate cases." (PMID 32727465, 2020). "Following PBMC activation with anti-CD3/CD28 antibodies, IL-10 showed lower levels, while IL-18 showed higher levels in supernatants of PBMCs from COVID-19 patients." (PMID 33634100, 2020). "The serum levels of IL-6, MCP-1, and IL-10 in the severe COVID-19 patients were all relatively lower than the corresponding levels in our three cohorts of CRS patients (sepsis, ARDS, and burns)." (PMID 32826331, 2020). "IL-10, an anti-inflammatory cytokine, which was increased in severe COVID-19 patients, was correlated with disease activity of AOSD." (PMID 33552062, 2020). "The pathogenesis of COVID-19 involves a potent inflammatory response, involving a complex group of mediators including IL-6 and IL-10." (PMID 32475230, 2020). "IL-10 is also elevated in COVID-19 patients; however, the overall role of the PD-1/PD-L1 axis in acute viral infections, and COVID-19 in particular, is less clear." (PMID 33003471, 2020). "Low IFNγ response to the SARS-CoV2 and high levels of immunosuppressive cytokines such as IL-10 in both COVID-19 and dengue during early illness is likely to result in an altered antiviral response." (PMID 33199778, 2020). "ICU-community-acquired pneumonia patients had inflammatory cytokine concentrations between stable and ICU COVID-19 patients but higher IL-10 concentrations." (PMID 33142828, 2020). "Within COVID-19 patients, serum IL-6 and IL-10 levels are significantly higher in critical group (n = 17) than in moderate (n = 42) and severe (n = 43) group." (PMID 32475230, 2020). "Neutrophils, C-reactive protein and several cytokines (as IL-6, TNF, IL-10) are increased in COVID-19, and this elevation is correlated with disease severity and death." (PMID 32733490, 2020). "Through further analysis of the prognosis in diabetic patients with severe COVID-19, it was found that lymphocyte count ≤0.45×109/L, LDH >600 U/L, hsCRP >90 mg/L and IL-10 >10 U/mL were associated with poor prognosis." (PMID 33382747, 2020). "These researchers further discovered that the anti-inflammatory IL-10 is notably (fourfold) lower in samples from COVID-19 patients compared to the healthy control." (PMID 32876941, 2020). "Interleukin 6 (IL-6) was elevated in total COVID-19 patients as well as in the severe group, while IL-10 was increased only in severe cases." (PMID 32669467, 2020). "Our findings revealed a significantly associated with elevated levels of anti-inflammatory cytokines involving IL-6 and IL-10 among severe and expired patients with COVID-19." (PMID 32822430, 2020). "Our previous preliminary study of 21 patients with COVID-19 exhibited that levels of sIL-2R, IL-10, TNF-α, hsCRP, Fer, and LDH were higher in the severe group than in the moderate group." (PMID 32854750, 2020). "As observed in MERS, SARS-CoV-1, and COVID-19 patients it is understood that initially delayed but gradual increase in cytokines like IL-1β, IFN-γ, IL-6, IL-8, and IL-10 is the main cause of rapid sepsis progression." (PMID 33634060, 2020). "A study indicated that COVID-19 patients treated in the intensive care unit with severe clinical features had a high level of innate cytokines IL-2, IL-10, IL-7, TNF-α, chemokines IP-10, MCP-1, and MIP-1A." (PMID 33101440, 2020). "The underlying pathophysiology of COVID-19 involves a maladaptive immune response to SARS-CoV-2 infection with increased levels of IL-6, IL-10, IL-2 and TNFα produced by macrophages, and fewer CD4+ and CD8+ T cells, but no significant changes in B-cell counts." (PMID 32399655, 2020). "Similar to our findings in patients with bacterial CRS, the serum concentrations of IL-6, MCP-1, and IL-10 in all patients with severe COVID-19 were significantly elevated compared with those in healthy controls." (PMID 32826331, 2020).
COVID-19 (continued). "In fact the serum IL-10 levels in early illness in those who progressed to develop DHF were 25 fold higher than in those who developed severe COVID-19." (PMID 33199778, 2020). "In Castleman disease, IL-6 is elevated in conjunction with TNFα, IL-1β and IL-10 as in severe COVID-19; however, vascular manifestations are unusual in this condition." (PMID 32629875, 2020). "COVID-19 patients have high levels of circulating interleukin 2 receptor (IL-2R), IL-6, IL-10 and tumor necrosis factor α (TNFα)." (PMID 33365277, 2020). "ICU-COVID-19 patients had the highest concentrations of IL-1β, IL-6, IL-6 to IL-10 ratio, and tumor necrosis factor receptor superfamily member 1A (TNFR1)." (PMID 33142828, 2020). "Insight into the inflammatory profiles shows that IFN-γ, together with IL-6 and IL-10, increased in patients with a severe type of COVID-19 compared to those with a mild type." (PMID 33133104, 2020). "Ki-67 expression strongly correlated with CRP levels, and with systemic levels of the cytokines IL-6, MCP-1, IP-10 and IL-10, cytokines that were enhanced in COVID-19 patients and tracked with severity." (PMID 32943497, 2020). "IL-6 and IL-10 were detected in supernatants from resting PBMCs from COVID-19 patients and were increased 225- and 6-fold, respectively, after co-culture (p = 0.0039 by Wilcoxon-matched pairs test)." (PMID 33634100, 2020). "A literature search was performed using the databases PubMed, EMBASE, and Web of Science to collect the levels of cytokine including IL-1β, IL-6, IL-18, TNF-α, IL-10, and ferritin in severe COVID-19 patients." (PMID 33552062, 2020). "As cytokine storms played a critical role in the deterioration of COVID-19, we also detected the Th1/Th2 cytokines including IL-2, IL-4, IL-6, IL-10, TNF-α, and IFN-γ in patients infected with COVID-19." (PMID 33061829, 2020). "In fact, IL2RA+CD4+ T-cells from severe COVID-19 patients expressed Th1, Th2, and IL-10 signature genes more frequently whereas Th17 differentiation was suppressed in IL2RA+ T-cells from both groups." (PMID 33178221, 2020). "Here we show that the percentages of different types of Tregs are increased in peripheral blood from COVID-19 patients, and that their plasma contains high amounts of the inhibitory cytokine IL-10." (PMID 32632085, 2020). "The comparison of cytokine concentrations in supernatants of PBMCs from COVID-19 patients and healthy subjects indicated that T lymphocytes from COVID-19 patients have lower ability to produce IL-10 and higher ability to produce IL-18 following activation." (PMID 33634100, 2020). "We first compared the levels of IFN-γ, TNF-α, IL-2, IL-4, IL-6 and IL-10 in serum samples from control group and COVID-19 patients." (PMID 32475230, 2020). "In contrast, patients with COVID-19 demonstrated activation of both Th1 and Th2 immunity, culminating inexpression of IFNγ, IL-1β, IL-4, and IL-10." (PMID 32742855, 2020). "Among these immune system modulators, IL-6 and IL-10 showed a positive correlation with mild COVID-19 group while IL-6 showed a good correlation with severe cases." (PMID 32948238, 2020). "We conclude that in severe COVID-19 initial innate responses, primarily type I interferon, are suppressed or sabotaged which results in an early interleukin (IL)-6, IL-10 and IL-1β-enhanced hyperinflammation." (PMID 34192268, 2020). "This study emphasizes the role of genetic variation in IL-10, particularly the protective effect of the GG and AG genotypes and G allele, and highlights age as a key determinant in the clinical progression of ARDS among COVID-19 patients." (PMID 40761632, 2025). "Single nucleotide polymorphisms (SNPs) in the TNF-α, IL-6, IL-8, IL-10, CCL5 and CXCL6 genes have been found to be associated with COVID-19 severity, suggesting that SNPs could help explain COVID-19 outcomes." (PMID 40881695, 2025). "Similarly, COVID-19 patients with elevated IL-10 levels uponadmission, were more likely develop severe disease." (PMID 40026520, 2025).
COVID-19 (continued). "In AdV, similarly as reported in COVID-19, an increase in IL-10 might indicate a failed attempt to suppress the hyperinflammatory response." (PMID 39858309, 2025). "Given its role in hyperinflammatory conditions, IL-10 could be significant in diseases like cancer, COVID-19, and post-COVID-19 syndrome." (PMID 40771803, 2025). "Decreased IL-10 and increased MIP-1β, sICAM-1, and P-selectin levels were associated with greater disease severity, emphasizing the critical importance of these markers in understanding and managing COVID-19." (PMID 41583455, 2025). "Our preceding findings suggested that the prolonged elevation of IL-10 and IL-12p70 induced by COVID-19 might exert a long-term influence on the efficacy of ICI therapy." (PMID 41157586, 2025). "The cytokine storms are characterized by significant induction of specific cytokines such as IL-6, IL-2, IL-7, GM-CSF, and IFN-γ in COVID-19 patients, which are different from other respiratory viruses with the increase in cytokines such as IL-2, IL-10, IL-4, or IL-5." (PMID 41002992, 2025). "When analyzing by disease severity, IL-2 and IFN-γ levels were higher in severe COVID-19 patients, indicating strong T-cell activation and a heightened immune response, while IL-10 was marginally higher in mild cases, suggesting a protective anti-inflammatory response." (PMID 40557167, 2025). "Furthermore, the majority of patients with severe COVID-19 exhibit markedly elevated serum levels of pro-inflammatory cytokines, including interleukin (IL)-6, IL-1β, IL-2, IL-8, IL-10, interferon (IFN)-α, IFN-γ, and tumor necrosis factor (TNF)." (PMID 41200104, 2025). "Since SP-D and IL-10 play prominent roles in the progression of COVID-19, the authors believe that their expression levels could reflect disease severity and pulmonary fibrosis progression." (PMID 40160824, 2025). "In addition, an imbalance in the systemic inflammatory response, marked by an increased IL-6/IL-10 ratio, is one of the possible factors contributing to the severity of primary open-angle glaucoma, gastric cancer, or COVID-19 patients." (PMID 40430444, 2025). "Additionally, EA individuals with COVID-19 showed increased production of IL-10 compared to NEA individuals." (PMID 40165959, 2025). "Furthermore, increased levels of IL-6 and IL-10 correlate with COVID-19 severity, and the dysregulated Th1 immune response in critically ill patients reinforces this theory." (PMID 40690446, 2025). "Increased serum interleukin-10 levels in COVID-19 patients may serve as both an anti-inflammatory mechanism and an immunosuppressive biomarker." (PMID 40552037, 2025). "The observed heterogeneity in IL-10 levels across different studies highlights the complexity of immune responses in COVID-19, indicating that IL-10 may be more indicative of generalized immune dysregulation than inflammation alone." (PMID 41585373, 2025). "Recent studies on SARS-CoV-2 revealed that COVID-19-associated cytokine storms (CSs) show elevated levels of IL-1 beta, IL-6, CXCL10, TNF alpha, IFN gamma, MIP 1 alpha, and 1 beta, as well as MCP-1, GM-CSF, VEGF, and IL-10." (PMID 40358160, 2025). "However, our study identifies ferritin and IL-10 as pivotal biomarkers for predicting glucocorticoid responsiveness in severe COVID-19, addressing a critical gap highlighted by the RECOVERY trial’s subgroup heterogeneity." (PMID 41426569, 2025). "Furthermore, serum from patients with severe COVID-19 significantly stimulated the production of IL-1ra and IL-10 compared to HV." (PMID 41583455, 2025). "Some studies have reported lower levels of IL-10 in critical-ill COVID-19 patients." (PMID 40508859, 2025). "For SLE and COVID-19 severity, IL-6 and IL-10 emerged as key genes (DC>8.0, BC>17.0, and CC>0.7)." (PMID 40643149, 2025).